IL6 (interleukin 6)
Diseases named in the same sentence as IL6 in open-access papers (continued):
Sharing a sentence is not in itself a finding about the gene and the disease.
glioma (continued). "In contrast, IL-6 silencing abrogated the effects of RTVP-1 on glioma cell migration and expression of the mesenchymal markers (e.g., fibronectin and α-SMA)." (PMID 36923251, 2023). "A prediction model based on the IL6/JAK/STAT signaling pathway was constructed using the LASSO-COX dimension reduction analysis to predict the OS of glioma patients." (PMID 37452092, 2023). "Further study of the downstream signaling pathways of IL-6 will help to understand its role in glioma and its clinical application." (PMID 38259287, 2023). "Given its role in facilitating a glycolytic phenotype and glioma survival and proliferation, IL-6 is an interesting target for glioma therapy." (PMID 38030881, 2023). "Levels of IL-6 found in serum and cerebrospinal fluid corresponded to glioma grade, with significant reduction in levels following resection." (PMID 38188300, 2023). "The opposite was observed for IL-6 in glioma-neutrophil (1:30) experimental group, in which IL-6 production was 10 times higher." (PMID 37292196, 2023). "miR-155-3p expression is also upregulated in hypoxic glioma cells in a time and IL-6 dose dependent manner, with induction increasing up to 24 h and IL-6 inhibition causing attenuation of miR-155-3p expression." (PMID 35611569, 2022). "The results indicated that CLCF1 achieved broader and more reliable prognostic ability than IL-6 in gliomas." (PMID 35265072, 2022). "In the peripheral monocytes of glioma patients, IL-6 levels are greatly increased compared with control patients." (PMID 35054779, 2022). "MiR-155-3p and interleukin 6 (IL-6) were highly expressed in hypoxic glioma-derived exosomes, and such exosomes also induced M2-like macrophage polarization and eventually promotes glioma progression." (PMID 35444652, 2022). "As previously reported, the IL6/JAK/STAT3 pathway was involved in the B7-H4(B7x)-mediated cross-talk between glioma-initiating cells and macrophages." (PMID 36233633, 2022). "On the one hand, glioma is a highly pro-inflammatory tumor since the abundant secretion of pro-inflammatory factors, such as IL-1β, IL-6, and high mobility group box protein (HMGB1) through the autocrine or paracrine mechanism accelerates tumor growth." (PMID 35990696, 2022). "TNF-α has been shown to induce IL-6 release from C6 glioma cells by modulating NFκB transcriptional activity." (PMID 35992852, 2022). "Microglia can regulate STAT 3 and NF-κB activity via mTOR, promote the immunosuppressive microglia phenotype to promote glioma immune escape, and upregulate their own IL-6 secretion via TLR4 as a mitogen for glioma stem cells." (PMID 36497459, 2022). "The co-culture of astrocytes and glioma cells enhanced IL-6 secretion by TAAs, thus promoting GBM migration and invasion." (PMID 35448036, 2022). "Further experiments showed that IL-6 and miR-155-3p induced M2-like macrophage polarization through the IL-6-pSTAT3-miR-155-3p-autophagy-pSTAT3 positive feedback loop, contributing to glioma progression." (PMID 35600367, 2022). "Kv channel blocker 4-AP can inhibit the secretion of IL-6 and IL-1, thereby inhibiting glioma cell proliferation." (PMID 36703789, 2022). "Past studies reported that IL-6 directly influences the invasion of gliomas by activating the STAT3 pathway." (PMID 36605437, 2022). "This renounces the antitumor activity and contributes to glioma invasion, releasing multiple cytokines, i.e., IL-1β, IL-6, IL-8, IL-10, and TNF-α." (PMID 35454935, 2022). "Although the glioma microenvironment is strongly immunosuppressive, M2-phenotype microglia and Treg, glioma cells still produce pro-inflammatory cytokines, such as IL-6." (PMID 35053377, 2022). "Interleukin 6 (IL-6) has been shown to be a factor involved in the malignant progression of glioma —it promotes regeneration, invasion, and angiogenesis." (PMID 35626018, 2022).
glioma (continued). "While CCL2 levels were similar for glioma cells co-culture with WT or CD44-/- microglia, IL-6 mRNA levels were reduced by half in glioma cells co-cultured with CD44-/- microglia, compared to WT." (PMID 35992852, 2022). "Co-culture of mast cells with glioma cells induces the expression of serglycin, CD44, ZEB1, vimentin, CXCL10, CXCL12, and TNF-α in glioma cells and IL-6 and CXCL1 in mast cells, creating an inflammatory milieu that induce glioma cell aggressiveness." (PMID 35494005, 2022). "High DDR score gliomas exhibited the enrichment of multiple immune activation pathways including IL-6/JAK/STAT3 pathway, interferon-gamma response, inflammatory response, and antigen processing and presentation." (PMID 35720326, 2022). "Our ELISA results showed decreased secretion of IL-6 from glioma cells in response to FAT1 knockdown." (PMID 35720420, 2022). "CCL2 released from glioma is a critical chemokine for TAMs and simultaneously triggers IL-6 release from microglia, thereby promoting the invasiveness of glioma cells." (PMID 35600367, 2022). "The NF-κB pathway affects the production of inflammatory factors such as IL-6 and IL-8 to regulate the tumor microenvironment and promote the development of glioma." (PMID 35345443, 2022). "And CLCF1 as a member of the IL6 family had a better predictive value for prognosis and immunotherapy response in glioma than that of IL6 and other IL6 family members." (PMID 35265072, 2022). "TAAs promote glioma invasion through the activation of several signaling pathways, such as nuclear factor kappa-B (NF-κB), interleukin (IL)-6/JAK/STAT, and sonic hedgehog (SHH) signaling." (PMID 35448036, 2022). "The expression of IL-6 often remains at a high level in gliomas, especially GBM, which results in the overactivation of the JAK2/STAT3 pathway and induces stronger EMT." (PMID 36338770, 2022). "The Tgfb3, Il6, and Il23a genes were strongly expressed in DCs cocultured with dying glioma cells pulsed with PS-PDT or with MTX (positive control) compared with the control group." (PMID 36539408, 2022). "Recently, hypoxic glioma-derived exosomes containing IL-6 and miR-155-3p were shown to activate the STAT3 pathway leading to autophagy which induced M2 polarization and promoted glioma progression." (PMID 35267626, 2022). "The levels of sHLA-G are also highly negatively correlated with the concentration of pro-inflammatory cytokine IL-6 and positively with the IL-10/IL-6 ratio in plasma of glioma patients." (PMID 35626255, 2022). "Consistent with this, studies have demonstrated that tumour progression in glioma is driven by an increase in proliferation and migration, and MSCs increase proliferation and maintain stemness in glioma via the IL‐6/gp130/STAT3 pathway." (PMID 35908277, 2022). "HGGs expresses a variety of immune-suppressive cytokines, including TGF-β, IL-10, IL-4, IL-6, and IL-13, all of which impede the anti-glioma immune response directly or indirectly." (PMID 36186781, 2022). "Further experiments showed that IL-6 and miR-155-3p induced M2-like macrophage polarization via the IL-6-pSTAT3-miR-155-3p-autophagy-pSTAT3 positive feedback loop, which promotes glioma progression." (PMID 33828078, 2021). "We then show that FOXS1 expression in glioma cells was increased by secretion of IL-6 in conditioned media, which originated mainly from the CD90low gaMSC subpopulation." (PMID 34256854, 2021). "Treatment with IL-6 pathway blockade via its receptor (IL-6R, tocilizumab) or binding soluble IL-6 (siltuximab) has been shown to inhibit glioma growth in vitro and reduce the expression of coinhibitory molecules such as PD-L1 on infiltrative myeloid cells." (PMID 33498872, 2021). "Microglia treated with glioma-conditioned medium (GCM) from primary cell lines increased the expression of genes encoding PDGFβ, SDF-1α, IL-6, IL-8, and EGF." (PMID 34944779, 2021).
glioma (continued). "In summary, we demonstrated that H-GDE-derived IL-6 and miR-155-3p can induce M2-like macrophage polarization via the IL-6-pSTAT3-miR-155-3p-autophagy-pSTAT3 positive feedback loop, which promotes glioma progression." (PMID 33828078, 2021). "As expected, we found that knockdown of TMEM44-AS1 reduced the recruitment of EGR1 to the promoter of IL-6 in LN-18 and U251 glioma cells." (PMID 34696771, 2021). "The interaction of pro-inflammatory IL-6 with Akt contributed to chemotherapeutic resistance and glioma genesis." (PMID 34439380, 2021). "The double-immunofluorescence staining revealed that the co-expression of COL1A1 with IL-6 was found in WHO II-IV grade glioma tissues." (PMID 34034744, 2021). "The overall survival analysis revealed that IL6 expression was predictive of poor prognosis in eight tumors including kidney clear cell carcinoma (log rank value: 31.46) and lower grade glioma (log rank value: 12.38) that showed the highest log-rank values." (PMID 34576335, 2021). "Both Dp44mT and bovine lactoferrin, as iron chelators, suppress growth, migration, and EMT process of glioma by inhibiting IL-6/STAT3 signaling pathway." (PMID 34568059, 2021). "Glioma cells secrete CCL2, which induces IL-6 secretion in microglia thereby increasing glioma invasiveness." (PMID 34503065, 2021). "Study indicates that M2-like macrophages drove glioma Vasculogenic mimicry (VM) through amplifying IL-6 secretion in glioma cells via PKC pathway." (PMID 34540695, 2021). "GSCs also have cross talk with microglia and recruit GAM at glioma tumor site; GSCs-triggered GAMs release pro-inflammatory cytokine IL-6 via TLR4 signaling which is activated by GSCs-produced tenascin-C to promote glioma growth." (PMID 34715891, 2021). "Destabilization of the BBB was associated with inflammatory factors, such as interleukin-6, interleukin-8 and VEGF-A, produced by the glioma cells." (PMID 33668807, 2021). "The results of this study showed that 25, 100, 200 μM of Wogonin inhibited the levels of these inflammatory factors in U251 glioma cells, and the IL-1 and IL-6 levels decreased in a dose-dependent manner with the increase in Wogonin concentration." (PMID 33897434, 2021). "We confirmed that p38MAPK and IL-6 signaling pathway-associated genes were inhibited in TMEM44-AS1 knockdown LN-18 and U251 glioma cells." (PMID 34696771, 2021). "IL‐6 induces invasion and migration in glioma cells through JAK‐STAT3, MAPK and PI3K/AKT signalling pathways, and its expression is closely related to prognosis." (PMID 34216174, 2021). "Targeting IL6 with tocilizumab significantly attenuated the expression of cancer stemness core genes in glioma." (PMID 33576874, 2021). "Among them, IL6 independently correlated with either age, prognosis, or the grade of the glioma, and activates STAT3, which is a reciprocally regulated cytokine network in tumor cells, including inflammation and angiogenesis factors such as IL-810." (PMID 34593910, 2021). "IL-6 increased the expression of FOXS1 in glioma cells compared to the control (DMEM medium) group, similar to gaMSCs." (PMID 34256854, 2021). "An in vitro study in murine microglial BV2 cells showed microglial cell activation by conditioned medium from glioma cells via upregulating mRNA expression of inducible nitric oxide synthase (iNOS), interleukin (IL)-1β, IL-6, TNF-α, and COX-2." (PMID 34439380, 2021). "Overall survival was lower in patients with high IL6 expression in their glioma samples and in the glioma samples from TCGA database, than in patients with low IL6 expression." (PMID 33576874, 2021). "The uncontrolled expression of IL-6 in the central nervous system is usually closely related to the onset of neurodegenerative diseases and gliomas." (PMID 33897434, 2021). "In contrast to PDGFα, PDGFβ, and SDF-1α, whose functions appear to be patient-specific, EGF and IL-6 are implicated in Pyk2- and FAK-mediated glioma cell proliferation in all subjects evaluated." (PMID 34944779, 2021).
glioma (continued). "Co-culture of glioma cells and NKTs showed miR-92a expressing in glioma cells played a key role in inducing the elevated expression of IL-6 and IL-10 in NKTs." (PMID 34603399, 2021). "Suppression of IL-6 production by MDZ in different cell types including glioma cell, Jurkat-T cell or human peripheral blood mononuclear cells (PBMCs) had been previously reported." (PMID 34281255, 2021). "Glioma-derived pro-inflammatory factors, IL-1β, IL-6, TNF-α, and COX-2, were found to accelerate p38 MAPK phosphorylation." (PMID 34439380, 2021). "The expression of TGF-β was positively correlated with IL6 expression in glioma samples, further validated by analysis of the TCGA database." (PMID 33576874, 2021). "In vivo bioluminescent imaging showed that nude mice implanted with glioma cells and IL-6- or miR-155-3p-overexpressing macrophages had stronger bioluminescence signals than those in the control group." (PMID 33828078, 2021). "The results showed that macrophages overexpressing IL-6 or miR-155-3p significantly promoted glioma cell proliferation and migration, which were inhibited by S3I-201." (PMID 33828078, 2021). "It was found that exposure of glioma cells to IL-6 (50 ng/ml) increased the expression of p-STAT3, while co-incubation of β-elemene abolished such activation." (PMID 34257541, 2021). "A few studies have investigated the interactions between TAN and glioma cells, and identified IL-6 and IL-8 as tumor-secreted key factors for TAN activation." (PMID 33766119, 2021). "TLR-4 activation in human glioma U251 cells stimulated the production of cytokines (IL-1β, IL-6, IL-8, and TNFα) and increased the expression of stem cell markers such as CD133 and CD34." (PMID 34439380, 2021). "Increasing evidence shows that the activation of IL6-mediated JAK2/STAT3 signaling is frequently associated with glioma, and promotes the cell growth, proliferation, and invasion of glioma cells." (PMID 33858489, 2021). "Then, we detected and compared the content of IL-6 and miR-155-3p between H-GDEs and normoxic glioma-derived exosomes (N-GDEs) and found that the expression levels of IL-6 and miR-155-3p were higher in H-GDEs than in N-GDEs." (PMID 33828078, 2021). "HOXB5 was overexpressed in glioma and transcriptionally regulated IL6 expression and promoted the proliferation of GSCs via JAK2/STAT3 signaling." (PMID 33858489, 2021). "Human GBM cell lines and cultured primary glioma cells can secrete a large amount of IL-1β, IL-6 and IL-8, and promote tumor growth in an autocrine or paracrine way." (PMID 34830775, 2021). "It has been reported that there are many kinds of molecules in the cerebrospinal fluid of glioma patients, such as IL-6 and miR-21, that have significantly higher levels than those in normal people." (PMID 34211612, 2021). "The results described that EZH2 silencing significantly reduced the secretion of MIP-3α and IL-8 and elevated the secretion of IL-6 in nude mice with glioma." (PMID 33363140, 2020). "After C6 glioma cells were treated with IL-6 signaling elicitors, the total cell populations were measured daily by the WST-1 assay for five days, with images taken on day three." (PMID 33227992, 2020). "From RT-qPCR results, with the increase of glioma grade, the expression of IL-6 in glioma clinical samples showed a downward trend, while expression of EZH2, IL-8, and MIP-3α exhibited an upward trend." (PMID 33363140, 2020). "Interleukin-6 (IL-6) has been suggested to induce the astrocytic differentiation of C6 glioma cells." (PMID 33227992, 2020). "In TNF-α/IL-6/sIL-6R treated glioma cells, STAT3 can be phosphorylated (p-STAT3) as a transcription factor to participate in IL-6 signaling." (PMID 33227992, 2020). "Th2-cytokine (IL-6/IL-8) are both considered major regulators of glioma cell growth and invasiveness." (PMID 33511267, 2020). "We examined the expression of the Il-6 gene in a tumorigenic C6 glioma cell line treated with IL-6, IL-6/sIL-6R, and TNF-α/IL-6/sIL-6R." (PMID 33227992, 2020).
glioma (continued). "The use of other stimulators of IL-6 signaling, including IL-6 and IL-6/sIL-6R, elicited lower levels of glioma cell differentiation." (PMID 33227992, 2020). "The results showed that, compared to control cells, TNF-α/IL-6/sIL-6R treated glioma cells formed more gap junctions with nearby cells." (PMID 33227992, 2020). "PD-L1 expression was found to be dependent on IL-6; inhibition of IL-6 signaling diminished expression of PD-L1, leading to increased survival and reduced tumor growth in orthotopic murine glioma model." (PMID 32765498, 2020). "After treatment with IL-6 signaling elicitors, glioma cells were seeded at one cell per well and allowed to grow for 6 days." (PMID 33227992, 2020). "Interleukin 6 (IL-6) upregulates the expression of glial fibrillary acidic protein (GFAP) in C6 glioma cells, indicating that it is able to induce the differentiation of these cells." (PMID 33227992, 2020). "Immunofluorescence results depicted that silencing EZH2 by lentivirus obviously reduced the expression of M2 macrophage polarization-related indicators (CD206, MIP-3α, and IL-8) but potently increased the expression of IL-6 in the glioma tissues of nude mice." (PMID 33363140, 2020). "Taking these two assays into consideration, it was concluded that TNF-α/IL-6/sIL-6R treatment decreased the tumorigenicity of the C6 glioma cell line." (PMID 33227992, 2020). "YKL-40 increases transiently after glioma surgery, whereas IL-6 has been shown to decrease, making it very important to standardize time of blood-sampling to gain consistent results." (PMID 32363159, 2020). "One study illustrated that glioma-derived CCL2 acts upon CCR2-bearing microglia to produce IL-6, which then stimulates gliomas." (PMID 32194542, 2020). "Together, these data suggest that glioma cells can stimulate the expansion of MDSCs by secreting numerous well-studied factors (IL-6, IL-10, VEGF, PGE-2, GM-CSF, and TGF-β2)." (PMID 32391020, 2020). "Meanwhile, immunofluorescence depicted that the expression of MIP-3α and IL-8 was strikingly declined but IL-6 expression was remarkably elevated in co-cultured M2 macrophages after infection with Lenti-EZH2 in glioma cells." (PMID 33363140, 2020). "Subsequently, we further confirmed the expression of differentiation markers in TNF-α/IL-6/sIL-6R treated glioma cells." (PMID 33227992, 2020). "We had initially demonstrated that FAT1 is a major contributor to pro-tumorigenic inflammation in gliomas driving the upregulation of pro-inflammatory cytokines like IL6 and IL1ß and also COX2 via AP1 activation." (PMID 31992226, 2020). "Previous studies investigating effect of either plasma or serum IL-6 levels on glioma survival mostly involve small cohorts and use a range of cut-offs, sampling times, and methods of detection." (PMID 32363159, 2020). "In this study, we provide an alternative method by which tumorigenic C6 glioma cells can be efficiently differentiated by enhanced IL-6 signaling." (PMID 33227992, 2020). "Several studies have shown that IL-6 is a crucial cytokine in glioma development and is important for glioma proliferation, invasion, and differentiation." (PMID 32194542, 2020). "It is therefore conceivable that FTY720 can target the glioma microenvironment by inhibiting microglial MAPK-mediated IL-6 secretion downstream of CXCR4 internalization." (PMID 32194542, 2020). "Altogether, FTY720 decreased microglial MAPK-mediated IL-6 secretion to suppress the migration and invasion of glioma." (PMID 32194542, 2020). "The role of IL-6 signaling was confirmed in the cyclic adenosine monophosphate (cAMP) induced differentiation of C6 glioma cells." (PMID 33227992, 2020). "Even in brain tissue, IL-6 can be expressed by certain astrocytoma and glioma lines under certain stimulation." (PMID 31269787, 2019). "Our meta‐analysis indicates that increased circulating IL‐6, IL‐8, IL‐17, TNF‐α, TGF‐β, and CRP levels are significantly associated with increased glioma risk." (PMID 31599129, 2019).